KASH5 (KASH domain containing 5)
Description:
As a component of the LINC (LInker of Nucleoskeleton and Cytoskeleton) complex, involved in the connection between the nuclear lamina and the cytoskeleton. The nucleocytoplasmic interactions established by the LINC complex play an important role in the transmission of mechanical forces across the nuclear envelope and in nuclear movement and positioning. Required for telomere attachment to nuclear envelope in the prophase of meiosis. Required for rapid telomere prophase movements implicating a SUN1/2:KASH5 LINC complex in which SUN1 and SUN2 seem to act at least partial redundantly. Required for homolog pairing during meiotic prophase in spermatocytes and probably oocytes. Essential for male and female gametogenesis. Recruits cytoplasmic dynein to telomere attachment sites at the nuclear envelope in spermatocytes. In oocytes is involved in meiotic resumption and spindle formation.
Synonyms: CCDC155; FLJ32658; POF22; SPGF88
Tractability: Antibody: UniProt predicts a signal peptide or a membrane-spanning region.
Gene: Protein-coding gene on chromosome 19 (49,388,219 to 49,417,990, forward strand). Ensembl gene ENSG00000161609.
Subcellular location: Nucleus outer membrane; Nucleus; Chromosome, telomere; Nucleus envelope
Gene Ontology:
Molecular function: protein binding; dynein complex binding; identical protein binding
Biological process: actin filament organization; chromosome localization to nuclear envelope involved in homologous chromosome segregation; homologous chromosome pairing at meiosis; spindle assembly; spindle localization; telomere localization
Cellular component: meiotic nuclear membrane microtubule tethering complex; nuclear envelope; chromosome, telomeric region; lateral element; meiotic spindle pole; nuclear outer membrane; nucleus
Genetic constraint (gnomAD): Loss-of-function variants: 70 observed, 78.22 expected, observed/expected ratio (o/e) 0.89, 90% interval 0.74 to 1.09. The upper end of that interval is the gene's LOEUF score, 1.09, which puts it in group 4 of 6, group 1 being the genes least tolerant of losing a copy. Missense variants: 649 observed, 671.79 expected, observed/expected ratio (o/e) 0.97, 90% interval 0.9 to 1.03. Synonymous variants: 260 observed, 256.78 expected, observed/expected ratio (o/e) 1.01, 90% interval 0.91 to 1.12.
Homologues: Orthologues: chimpanzee KASH5 (98% identical), macaque KASH5 (92% identical), pig KASH5 (82% identical), dog KASH5 (80% identical), rat Kash5 (73% identical), mouse Kash5 (72% identical), guinea pig KASH5 (69% identical). Paralogues in human: SSH1 (12% identical), SSH2 (11% identical), SSH3 (10% identical), DUSP16 (10% identical), STYXL1 (10% identical), STYXL2 (9% identical), DUSP8 (9% identical), DUSP4 (8% identical), DUSP9 (8% identical), DUSP5 (8% identical), DUSP7 (8% identical), DUSP1 (7% identical), and 19 more.
Diseases named in the same sentence as KASH5 in open-access papers:
KASH5 is named in the same sentence as 15 diseases in open-access papers, as found by Europe PMC text mining. Sharing a sentence is not in itself a finding about the gene and the disease. The quoted sentences say what the papers report.
Infertility (3 papers, 2021 to 2024). "In this study we show that the decreased hydrophobicity of the TMD is responsible for a mistargeting of the L535Q KASH5 away from the NE, and we suggest that this mislocalization is the mechanism by which the L535Q variant contributes to infertility." (PMID 33980926, 2021). "The human KASH5 variant that is associated with infertility is a T > A transversion at position 1604 in the cDNA40." (PMID 33980926, 2021). "In conclusion, we have investigated an infertility-associated variant in human KASH5 and shown that the amino acid substitution results in a changed TMD hydrophobicity." (PMID 33980926, 2021). "Among the retained variants, a frameshift mutation in KASH5 was identified recessively segregating with the infertility and recurrent miscarriage within the family; a missense variant in IZUMO1R was found heterozygous in the female patients and their father, but not present in the fertile sister." (PMID 36864840, 2023). "Since we could see clear colocalization of the MitoTracker Red CMXROS signal and the GFP L535Q KASH5 signal, we suggest that mitochondrial disfunction is an unlikely contributor to the infertility caused by the variant L535Q KASH5." (PMID 33980926, 2021). "Moreover, the KASH5 gene is highly expressed in the testis, and known phenotypes of the Kash5 knockout mouse model recorded in the FertilityOnline database are infertility in both sexes." (PMID 36864840, 2023). "Considering that all our patients do not present other symptoms except infertility/recurrent miscarriage, the KASH5 variant was thus identified as the variant most likely pathogenic for the reproductive defects of this family." (PMID 36864840, 2023). "While we are proposing that the L535Q substitution in KASH5 causes infertility by preventing RPM in meiosis, it is possible that the accumulation of L535Q KASH5 at the mitochondria could trigger mitochondrial stress and cytotoxicity leading to infertility." (PMID 33980926, 2021). "In humans, biallelic mutations in MAJIN have been reported in infertile males and those in KASH5 and TERB1 in infertile males and in females with POI." (PMID 39545410, 2024). "We suggest that the absence of KASH5 at the NE is the molecular mechanism for the infertility observed in patients that are homozygous for the L535Q KASH5 variant." (PMID 33980926, 2021).
male infertility (3 papers, 2021 to 2023). The inability of the male to effect fertilization of an ovum after a specified period of unprotected intercourse. "A recent study identified a variant in human KASH5 (L535Q) that correlated with male infertility associated with azoospermia." (PMID 33980926, 2021). "The KASH5 homozygous variant was found in two brothers affected by azoospermia, a severe type of male infertility characterized by a complete absence of spermatozoa production due to a spermatogenesis arrest." (PMID 33980926, 2021).
Azoospermia (2 papers, 2021 to 2023). Absence of any measurable level of sperm,whereby spermatozoa cannot be observed even after centrifugation of the semen pellet. "We suggest that this functional loss of KASH5 from the ONM is responsible for the azoospermia phenotype of these patients." (PMID 33980926, 2021). "Reverse-transcription analyses of the testicular cDNA revealed a similar level of KASH5 mRNA in the patient to that in the control man who was diagnosed with obstructive azoospermia." (PMID 36864840, 2023). "This mutation leads to the absence of KASH5 protein expression in testes and non-obstructive azoospermia (NOA) due to meiotic arrest before the pachytene stage in the affected brother." (PMID 36864840, 2023).
aneuploidy (1 paper, 2023). Chromosomal disorder consisting of the presence a chromosomal abnormality in which there is an addition or loss of chromosomes within a set. "Thus, we suspected that the KASH5 truncated protein retaining some function may be expressed in ovaries of patients, which allows the production of eggs with an abnormal number of chromosomes and fertilization, but the fetus consequently ended in spontaneous abortion due to aneuploidy." (PMID 36864840, 2023).
female infertility (1 paper, 2023). Diminished or absent ability of a female to achieve conception. "IZUMO1R is implicated in fertilization and barely expressed after fertilization, and Kash5 mutant mice exhibit male and female infertility due to meiotic defects." (PMID 36864840, 2023).
Miscarriage (1 paper, 2023). A pregnancy that ends at a stage in which the fetus is incapable of surviving on its own, defined as the spontaneous loss of a fetus before the 22th week of pregnancy. "In summary, we have provided genetic and functional evidence that a homozygous loss-of-function mutation in KASH5 leads to reproductive failure in both sexes with sexual dimorphism and bring forward KASH5 as a recurrent miscarriage-associated gene." (PMID 36864840, 2023).
Premature ovarian insufficiency (1 paper, 2023). Amenorrhea due to loss of ovarian function before the age of 40. "Very recently, homozygous splicing and missense mutations in KASH5 were reported in NOA men displaying zygotene arrest and women with premature ovarian insufficiency (POI), suggesting a potentially conserved role of KASH5 in humans." (PMID 36864840, 2023).
KASH5 also shares sentences with these, for which no sentence is quoted: carcinosarcoma (1 paper); mesothelioma (1); Oligomenorrhea (1); ovarian carcinoma (1); Parkinson’s (1); recurrent hydatidiform mole (1); schizophrenia (1); tumor (1).